RBMS1P1 (RNA binding motif single stranded interacting protein 1 pseudogene 1)
Synonyms: MSSP1; formerly RBMS1P
Gene: Processed pseudogene on chromosome 12 (66,234,079 to 66,235,234, reverse strand). Ensembl gene ENSG00000225422.
Diseases named in the same sentence as RBMS1P1 in open-access papers:
RBMS1P1 is named in the same sentence as 1 disease in open-access papers, as found by Europe PMC text mining. Sharing a sentence is not in itself a finding about the gene and the disease. The quoted sentences say what the papers report.
tumor (1 paper, 2022). "Univariate Cox regression analysis of clinical indicators revealed that T stage, N stage, M stage, pathologic stage, age, histological type, residual tumor, HSPA8P4, PHC1P1, RBMS1P1, LINC01303, and MSC-AS1 were meaningful, and the expression level of COL5A2 was also significant." (PMID 36447214, 2022).